NTMT2 (N-terminal Xaa-Pro-Lys N-methyltransferase 2)
Description:
Alpha N-methyltransferase that methylates the N-terminus of target proteins containing the N-terminal motif [Ala/Pro/Ser]-Pro-Lys when the initiator Met is cleaved. Specifically catalyzes monomethylation of exposed alpha-amino group of Ala or Ser residue in the [Ala/Ser]-Pro-Lys motif and Pro in the Pro-Pro-Lys motif. Predominantly functions as a mono-methyltransferase but is also able to di-/tri-methylate the GPKRIA peptide and di-methylate the PPKRIA peptide (in vitro). May activate NTMT1 by priming its substrates for trimethylation.
Synonyms: NTM1B; C1orf184; METTL11B; HOMT1B
Tractability: Small molecule: a structure with a bound ligand is known. PROTAC: a small molecule that binds it is known.
Target class: Enzyme; Transferase
Gene: Protein-coding gene on chromosome 1 (170,145,959 to 170,168,866, forward strand). Ensembl gene ENSG00000203740.
Subcellular location: Nucleus
Gene Ontology:
Molecular function: N-terminal protein N-methyltransferase activity; methyltransferase activity
Cellular component: nucleus; cytoplasm
Genetic constraint (gnomAD): Loss-of-function variants: 23 observed, 27.23 expected, observed/expected ratio (o/e) 0.84, 90% interval 0.61 to 1.2. The upper end of that interval is the gene's LOEUF score, 1.2, which puts it in group 5 of 6, group 1 being the genes least tolerant of losing a copy. Missense variants: 336 observed, 366.41 expected, observed/expected ratio (o/e) 0.92, 90% interval 0.84 to 1. Synonymous variants: 131 observed, 133.5 expected, observed/expected ratio (o/e) 0.98, 90% interval 0.85 to 1.13.
Homologues: Orthologues: macaque NTMT2 (98% identical), chimpanzee NTMT2 (95% identical), dog NTMT2 (95% identical), mouse Ntmt2 (94% identical), rat Ntmt2 (93% identical), pig NTMT2 (93% identical), rabbit NTMT2 (93% identical), guinea pig NTMT2 (92% identical), tropical clawed frog ntmt2 (72% identical), zebrafish ntmt2 (60% identical), Drosophila melanogaster Ntmt (32% identical), Caenorhabditis elegans homt-1 (31% identical). Paralogues in human: NTMT1 (40% identical).
Diseases named in the same sentence as NTMT2 in open-access papers:
NTMT2 is named in the same sentence as 4 diseases in open-access papers, as found by Europe PMC text mining. Sharing a sentence is not in itself a finding about the gene and the disease.
NTMT2 shares sentences with these, for which no sentence is quoted: cancer (4 papers); glioma (2); colorectal cancer (1); tumour (1).